CD5 (CD5 molecule)
Diseases named in the same sentence as CD5 in open-access papers (continued):
Sharing a sentence is not in itself a finding about the gene and the disease.
tumor (continued). "Immunohistochemically, the tumor cells of EATL are positive with antibodies directed against CD3, CD2, CD5, and CD8, but negative with CD56." (PMID 33546043, 2021). "The monomorphic and small to medium-sized tumor cells in most cases were positive for CD3, CD8, CD43, CD56, and negative for CD5, with round nuclei, obvious nucleoli, and pale cytoplasm." (PMID 34895266, 2021). "Expression of CD3, CD5, and CD8 was observed in reactive T lymphocytes surrounding tumor cells and not in tumor nuclei." (PMID 33585230, 2020). "The FL‐SJC cells were fully negative for CD23 and CD5 which were 8% and 5% positive, respectively, in primary FL cell, suggesting that the FL‐SJC cells have a higher purity than original tumour cells." (PMID 32459397, 2020). "Immunohistochemical analysis showed that the tumor cells were positive for CD20, BCL2, BCL6, and MUM-1 and were negative for CD5 and CD10." (PMID 33071959, 2020). "Immunohistochemically tumor cells were positive for Bcl2 and Cytokeratin AE1 + AE3, while infiltrated lymphocytes were positive for CD3 and CD5 and negative for CD99." (PMID 31655916, 2019). "Resistance of tumor cells to cytarabine correlated with the expression of Ki-67 (r = 0.33) and T-cell markers (CD2, r = 0.22; CD3, r = 0.25; and CD5, r = 0.14), but not with immaturity markers." (PMID 31067780, 2019). "Tumor cells are positive for CD20 and CD79a or abnormal expression of CD43, and negative for CD5, CD10 and Cyclin D1." (PMID 29489937, 2018). "In 22 dogs in which flow cytometry was performed, tumor cells in 15 dogs lacked expression of T (CD3, CD5) or B (CD21, CD22) cell markers." (PMID 28620611, 2017). "Immunohistochemical staining revealed that the large-sized tumor cells were positive for CD20, PAX-5, MUM-1 and BCL-2, and were negative for CD3, CD5, CD43, CD10, CD23, CyclinD1, CD138, CD30, ALK, CD56, MPO, S-100, TTF-1, thyroglobulin and calcitonin." (PMID 28841887, 2017). "Limited flow cytometric studies from the muscle tumor revealed an expansion of apparently large, surface immunoglobulin-negative, CD10 dim and CD19 positive, and CD5 negative cells." (PMID 27247818, 2016). "In our case, tumor cells were positive for BOB1, MUM1, and EBER-ISH, partially positive for CD79a, and negative for CD20, CD56, CD138, CD3, CD5, AE1/AE3, and HHV8, which was most consistent with plasmablastic lymphoma." (PMID 27034868, 2016). "We used surface staining against the B10/Breg markers CD5, CD1d and Granzyme B in combination with CD19 and were able to identify cells with a Breg phenotype in wild-type controls but not in tumor-bearing recipients of T and B cells (data not shown)." (PMID 27121060, 2016). "IHC revealed tumor cells positive for CAM 5.2, calretinin, CD5/6, and D2-40, but negative for carcinoembryonic antigen, HBME, and thrombomodulin." (PMID 27599565, 2016). "Immunohistochemical analysis indicated that the tumor was positive for TTF-1, NSE, chromogranin A and Ki-67, but negative for SYN, leukocyte common antigen, p63 and CD5/6." (PMID 25789020, 2015). "Immunohistochemical analysis indicated that the tumor was positive for TTF-1 and SYN, but negative for CD5/6." (PMID 25789020, 2015). "Immunohistochemical (IHC) staining of tumor cells expressed positivity for mature B cell markers CD20, CD19, CD10, CD23, CD45, and CD38 but negative for CD5,11c." (PMID 26380128, 2015). "RC cells had the following immunophenotype: positive for CD10, CD19, CD20, CD22, CD38, CD43, CD44, and CD79b and negative for CD3, CD4, CD5, CD8, CD11c, CD14, CD30, CD56, and CD200, which was identical to the primary tumor cells." (PMID 26515759, 2015). "Immunohistochemically, the epidermoid cells of the tumor were positive to pan-CK (AE1/AE3), CK5/6, CK7 and p63, but negative to CD5." (PMID 24444077, 2014).
tumor (continued). "Immunohistochemically, the tumor cells were strong positive for CD56, CD3ε, TIA1, and weak positive for LMP1, and negative for CD5, CD8, CD20, CD79a, CgA, Syn, SCLC, CK, EMA, CD99, CD10, TdT, PAX-5, and BCL-6." (PMID 23958352, 2013). "The immunohistochemistry staining showed that the tumor cells were diffusely positive for S-100, CD1a, langerin and CD68, but negative for CD3, CD5, CD20, CD21, CD30, CD38, CD56, CD79a, ALK, HMB-45, Melan-A, pan-cytokeratin and MPO." (PMID 23388086, 2013). "The cells derived from the tumor mass and the CLBL-1M cell line stained positive for CD11a, CD79αcy, MHCII and negative for CD3 and CD5." (PMID 22761949, 2012). "Immunohistochemical staining demonstrated that most tumor cells were positive for B- cell markers such as CD20, bcl-6, and multiple myeloma oncogene 1 (MUM1), whereas those same tumor cells were negative for CD3, CD5, CD10, or bcl-2 (data not shown)." (PMID 22927863, 2012). "Phenotypic analysis of these tumor cells revealed these cells are positive for B cell markers CD19+, CD5+, B220+, IgM+ and negative for T cell, NK or dendritic cell markers." (PMID 21269511, 2011). "Tumor cells typically express CD20, CD5, and Cyclin D1, while lacking CD10 and Bcl-6." (PMID 41585338, 2026). "The tumor cells were negative for CD3, CD30, CD5, and BCL-1." (PMID 39897193, 2025). "The immunohistochemical examination identified tumor proliferation with small B-cells, positive for CD20 (positive marker in B-cells), negative for Cyclin D1, negative for CD5 (positive marker in T-cells), with a kappa/lambda ratio of 5/1 (monoclonal dominance of kappa light chains)." (PMID 41189780, 2025). "Unlike what was observed for CD6, confronting PBMCs with tumor cell lines does not modify CD5 expression on immune cells, which suggests that despite its high structural homology with CD6, neither CD318 nor ALCAM had an impact on CD5 expression." (PMID 40391211, 2025). "The tumor cells typically do not express surface CD4, CD5, CD8, betaF1, or TRC delta." (PMID 38611591, 2024). "Through immunohistochemistry, the tumor cells were found to express B-cell markers, including CD20 and PAX5, and co-express the germinal center markers CD10, BCL6, and IgM, and they were found to be negative for BCL2, Cyclin D1, CD23, CD5, and TdT." (PMID 39768757, 2024). "None of the tumor cells expressed BCL2, CD3, CD5, MUM1, and CyclinD1." (PMID 37539011, 2023). "Typically, tumor cells are CD2+, CD3+, CD4+, CD8−, CD5+, and CD25+, and CD7 is often negative." (PMID 34830926, 2021). "Immunohistochemically, the tumor cells were negative for CD117 and CD5." (PMID 33819365, 2021). "The tumor cells in ETTL-1 express CD3 and CD7, but not CD4, CD8, CD5, or CD56." (PMID 33457319, 2020). "Immunohistochemically, the staining results of tumor cells in the small intestine and kidney were consistent; the tumor cells were positive for CD3, CD56, granzyme B, TIA-1, and perforin, while negative for CD4, CD8, CD5, Desmin, CD34, CKpan, CD20, CD30, SMA, CD79ɑ, and PAX8." (PMID 36199094, 2022). "Furthermore, the most consistent tumor cell phenotypes isolated from cattle with EBL are CD5+, CD6–, B1 low+, B2+, major histocompatibility complex class II+, and either sIgM+ or sIgM–; this indicates the involvement of the CD5+ B cell sub population rather than the CD5-B cell sub population." (PMID 23641811, 2013).
cancer (62 papers, 2014 to 2026). A tumor composed of atypical neoplastic, often pleomorphic cells that invade other tissues. "CD5-targeted therapies have shown benefits in cancer treatment, however, loss of CD5 is also associated with weaker antitumor responses." (PMID 40391211, 2025). "In contrast, the limited fratricide associated with CD5 2G (CD28) CAR-T-cells allowed for sufficient cellular expansion to exert antitumor activity toward T-cell malignancies." (PMID 37626869, 2023). "The increased abundance of the CD5 antigen‐like apoptosis inhibitor in the disease group may suggest an aggravation of local inflammation, as this protein is associated with diagnostic and prognostic markers in various cancer‐related clinical scenarios." (PMID 40457720, 2025). "Overall, our study reveals the E1 A → E1B switch as a key mechanism regulating CD5 expression in aging and underscores the broader implications of this switch in immunosenescence and immune dysfunction in aging and cancer." (PMID 40788503, 2025). "Hematological malignant cell lines were used as targets to assess the anti-cancer efficacy of CD5 CAR-NK cells." (PMID 41050660, 2025). "In contrast, CD5#11 showed a more balanced profile, achieving strong anti-cancer efficacy with lower toxicity." (PMID 41050660, 2025). "Cytotoxicity and degranulation assays were conducted using L1 cells to compare the toxicity of CD5 CAR-NK cells towards cancer and normal cells." (PMID 41050660, 2025). "Exploration of anti-CD5 therapies in treatment of cancer, alone and in combination with other immune therapeutic drugs, is warranted." (PMID 38487537, 2024). "CD5+cDC2 accumulate in inflamed psoriatic lesions and their diminished frequency in draining lymph nodes of cancer patients correlated with poor prognosis and response to checkpoint inhibitor therapy." (PMID 37539048, 2023). "In fact, the ability of natural antibodies produced by CD5+ B cells to recognize cancers of the stomach, colon, pancreas, esophagus, lung, prostate, breast, and skin (melanoma) through binding to carbohydrate moieties has been demonstrated." (PMID 37965337, 2023). "Based on the small number of data associating CD5 and CD6 with cancer, we cannot draw a clear conclusion and thus a question remains in mind: are they a potential link between PD and cancer?" (PMID 35055157, 2022). "Because of these T cell metabolic changes, CD5 has the potential to impact health and disease, such as chronic infection and cancer immunotherapy." (PMID 35327505, 2022). "Among them, 8 of 12 hub genes (EPHX3, SPINK7, FCRLA, MASP1, ZNF541, CD5, BEST2, ZAP70) seemed to be cancer-promoting genes as they were downregulated in the high-risk group." (PMID 35846149, 2022). "The inhibitory function of CD5 in T and B1a cell activation has positioned this receptor as a relevant player in the immune response against cancer." (PMID 34070159, 2021). "CD5 levels in naïve T cells are constantly tuned in the periphery by interactions with self pMHC complexes to maintain homeostasis; therefore, CD5 expression on TILs can be downregulated in response to low affinity for cancer antigens." (PMID 29701673, 2018). "Prior the emergence of antibody-based cancer treatments, results of clinical trials using anti-CD5 mAb have established moderated benefit in patients with chronic lymphocyte leukemia or cutaneous T-cell lymphomas." (PMID 30581443, 2018). "Whatever the case, the results warrant future studies exploring CD5 targeting to improve the efficacy of currently available immunotherapeutic approaches against cancer such as IL-10, TGF-β inhibitors or IL-2/anti-IL-2 mAb immunocomplexes." (PMID 29296231, 2017). "Likewise, CD5 levels gradually declined, with a more rapid reduction in cancer cells exhibiting high B7-H6 expression." (PMID 41050660, 2025).
cancer (continued). "Six of these—CD5, CTLA4, TIGIT, LAIR1, PDCD1, and TNFRSF14—encode proteins that have been identified as immune checkpoints, defined broadly as receptors on immune cells that are exploited by cancer cells to escape the immune response." (PMID 39887658, 2025). "The purported interaction between S100A4 and CD5 may have implications in other disease contexts, such as cancer, given the ability of CD5 to downregulate T cell response." (PMID 40078995, 2025). "CD5 expression on carcinoma cells may therefore affect the capacity of carcinoma cells to evade immune responses, but this hypothesis remains to be tested." (PMID 40242668, 2025). "Specific TIL subsets that have been shown to be associated with cancer prognosis vary across the studies and include CD3+, CD4+, CD5+, CD8+, CD45RA+, FOXP3+ and PD1+ TILs; however, CD3+, CD8+ and FOXP3+ TILs were commonly shown to associate with prognosis in many cancer types." (PMID 38704243, 2024). "In this sense, while ABCs might participate in follicular or extrafollicular clonal redemption, CD5+ B cells would seem to only participate in extrafollicular clonal redemption in cancer." (PMID 37965337, 2023). "Certainly, the role of CD5 and CD6 in PD-associated cancers should be furtherly investigated." (PMID 35055157, 2022). "CD5 is also expressed on Breg cells, which play a controversial role in cancer." (PMID 33287301, 2020). "As Ca2+ signaling plays a key role in T cell activation and function, controlling Ca2+ mobilization in T cells through CD5 expression could influence diverse areas of clinical research including metabolism, cancer treatments, and even cognitive behavior." (PMID 29701673, 2018). "Furthermore, to examine whether CD5 CAR-NK cells preferentially target cancer cells over normal cells when exposed simultaneously, we co-incubated with MOLT4, MNC, and CAR-NK cells at a ratio 1:1:1." (PMID 41050660, 2025). "This study also mentioned that CD5 and PD-1 could be used as immunotherapies in cancer treatment." (PMID 36514573, 2022). "Similarly, ex vivo treatment with a blocking anti-CD5 (clone 53–7.3) mAb increased the killing capacity of CD8+ T lymphocytes of mouse cancer (breast) cells concomitant with increased expression of markers for both T cell activation (i.e., CD69) and AICD (i.e., Fas, FasL)." (PMID 33287301, 2020). "Thus, differential CD5 levels among T cells in tumors and lymphoid organs can be associated with different levels of T cell activation and effector function, suggesting that CD5 may be a therapeutic target for immunotherapeutic activation in cancer therapy." (PMID 33584650, 2020). "Also, evaluation of biological effects provided by combination with other antibodies in a broader spectrum of malignancies could reveal CD5 as a potent target to control cancer." (PMID 30581443, 2018). "As such, CD5 may be a novel checkpoint therapy to regulate T cell activation and metabolism through altering Ca2+ mobilization, and could be used to affect neurological behavior, alter microbiome interactions, and treat cancer and autoinflammatory diseases." (PMID 29701673, 2018). "Current guidelines in the diagnosis of CLL/SLL require that the cancer cells express the antigens CD19, CD20, and CD23 (markers of mature B-cells) as well as CD5." (PMID 40385890, 2025). "In particular, among the four types of CD5 CAR-NK cells, #11 and #14 showed relatively high anti-cancer activities." (PMID 41050660, 2025). "In contrast, the biomarkers uPA, IL-18R1, EN-RAGE, CASP-8, MCP-2, TNFβ, CD5 and CXCL10, whose functions are related to cancer or inflammatory processes, had their expression inhibited." (PMID 39247198, 2024). "Candidate biomarkers such as IL-7, TWEAK, 4E-BP, CXCL5, and CD5 are all actively involved in cancer initiation and progression in previous reports, and the KEGG analysis also indicated cancer pathway enrichment." (PMID 38455059, 2024).
cancer (continued). "T cells undergoing beta-selection differentiate via sequential expression of co-receptors CD28, CD5, and CD2, exposing new signalling controls that are disrupted by a cancer therapeutic." (PMID 36283704, 2023). "Measurements of serum expression levels in cancer patients undergoing cisplatin treatment have earlier been explored for four of these inflammatory proteins, namely, FASLG, CXCL5, CD5, and IL-12." (PMID 35682983, 2022). "Blockade of CD5 also demonstrated increases in both CD4+ and CD8+ T cell responses to cancer, indicating that its inhibitory effects can be halted by antibody blockade." (PMID 35327505, 2022). "Some antigens, including CD5 and PSMA are rapidly internalized in cancer cells, leading to catabolism of the carrier-target complex and, specifically, radionuclide separation from the carrier molecule followed by its efflux from the cell." (PMID 26729091, 2015). "Lack of anti-cancer activity against CD5- U937 cells corroborates the antigen-specific response, serving as a negative control for CD5 targeting." (PMID 41050660, 2025). "CD5 CAR-NK cells demonstrated anti-cancer efficacy against MOLT4 cells with no significant aggressiveness against normal human immune cells." (PMID 41050660, 2025). "Both CD5 and CD30 are treated as classical targets for cancer therapy." (PMID 38468291, 2024). "In addition, we predicted the sensitivity of common anti-cancer drugs on prognostic signature, including CCR5, HMOX1, CTSC, CD5, BCL3, CDH1, TYROBP and CD38." (PMID 38767825, 2024). "This study aims to characterize the expression patterns of CD5 in different subsets of TCL and evaluate whether CD5 expression has a prognostic role in these cancers." (PMID 39410047, 2024). "Under a cancer context, it is known that STAT3 signaling regulates the CD5 expression, but in the TB context, this signaling has not been clarified; further studies are necessary to identify the molecules involved to favor the expansion of CD5+ B cells in LTB." (PMID 37375508, 2023). "CD5 and CD6 have been demonstrated to affect the immune response to cancers." (PMID 35983088, 2022). "Currently, there are bidirectional roles of CD5 and CD6 in cancer immunity." (PMID 35983088, 2022). "CD5 and CD6 molecules play a role in cancer and chronic lymphocytic leukemia." (PMID 35055157, 2022). "Interestingly, the study based on mouse models reported that the absence or blockade of CD5- and CD6-mediated signals resulted in the dysfunction of the immune response, subsequently enhancing cancer progression." (PMID 35055157, 2022). "The negative immunomodulatory properties of CD5 appear relevant in cancer immune response as supported by multiple evidences." (PMID 33287301, 2020). "As specific bacterium promotes cancer regression during CTLA-4 and PD-1 checkpoint blockades, a CD5 blockade in conjunction with bacterial selection may also improve immune response." (PMID 29701673, 2018). "IL3Rα, like CD5, is not cancer specific, and the consequence of CD5 CAR T cells is severe myeloablation." (PMID 30031396, 2018). "All seven patients with disease-specific mortality had CD5-negative carcinomas." (PMID 40242668, 2025). "However, they also inhibit the anti-cancer immune response by reducing the population of CD8 effector and memory T cells and suppressing the activation of T cells, as well as down-regulating the expression of CD161 and CD5 in various T cell subpopulations." (PMID 38348038, 2024). "Moreover, no statistical significance of CD5 expression on lymphocytes was detected between both groups of bitches with malignant tumors and the control group." (PMID 34438855, 2021). "In order to assess the in vivo use of sCD5 as a decoy receptor in cancer therapy, a transgenic mouse line that constitutively expresses the soluble portion of human CD5 (shCD5) under control of the non-tissue specific SV40 promoter and immunoglobulin μ heavy chain enhancer (Eμ) was developed." (PMID 33287301, 2020).